SMO (smoothened, frizzled class receptor)
Diseases named in the same sentence as SMO in open-access papers (continued):
Sharing a sentence is not in itself a finding about the gene and the disease.
osteosarcoma (continued). "To explore the involvement of Hh pathway in the pathogenesis of osteosarcoma, we investigated the expression and activation of the Hh pathway genes in osteosarcoma and examined the effect of inhibition of SMO by cyclopamine, a specific inhibitor of SMO or SMO shRNA." (PMID 20067614, 2010). "In addition, knockdown of SMO by SMO shRNA prevents osteosarcoma growth in vitro and in vivo." (PMID 20067614, 2010). "To extend these findings, we performed immunocytochemistry for SMO and GLI2, and found that only osteosarcoma cells expressed detectable levels of SMO and GLI2." (PMID 20067614, 2010). "In the present study, we found that Shh, Dhh, PTCH1, SMO, GLI1 and GLI2 transcripts were over-expressed in osteosarcoma cell line." (PMID 20067614, 2010). "To explore the involvement of aberrant Hedgehog pathway in the pathogenesis of osteosarcoma, we investigated the expression and activation of Hedgehog pathway in osteosarcoma and examined the effect of SMOOTHENED (SMO) inhibition." (PMID 20067614, 2010). "To determine whether activation of Hh-GLI signaling is required for osteosarcoma cell growth, we used cyclopamine, a pharmacological agent known to effectively block Hh-GLI signaling by inhibiting SMO activation." (PMID 20067614, 2010). "Whether the subcellular localization of SMO similarly effects the balance of canonical versus non-canonical Hh signaling in osteosarcoma is unknown." (PMID 37845394, 2023). "In addition, SMO, PTCH1, and GLI2 were over-expressed in osteosarcoma biopsy specimens'." (PMID 20067614, 2010).
brain tumors (7 papers, 2015 to 2023). "Presently, there are several ongoing clinical trials evaluating SMO inhibitors for the treatment of different types of brain tumors." (PMID 36010607, 2022). "Nowadays, the primary target used for development of Shh-pathway inhibitors in clinical trials is SMO, and there are several clinical trials for different types of brain tumors ongoing." (PMID 29558958, 2018). "Furthermore, in our study, mutations in two genes that are frequently mutated in brain tumors, PTEN and SMO, were found to correlate with inferior OS, regardless of the initially applied treatment approach." (PMID 27164089, 2016).
mesothelioma (7 papers, 2013 to 2025). A usually malignant and aggressive neoplasm of the mesothelium which is often associated with exposure to asbestos. "Higher SMO expression levels were associated with a shorter survival time and a poorer prognosis for patients with mesothelioma (P = 0.005)." (PMID 37139482, 2023). "Our analysis also showed that immune cell infiltration mechanisms were associated with SMO and GLI1 expression, and that CD4+ T cells, neutrophils, and macrophages have an important impact on mesothelioma development and prognosis." (PMID 37139482, 2023). "SMO and GLI1 in mesothelioma tissues detected high concordance between the diagnostic results of mesothelioma biopsy specimens and plasma cavity effusion specimens." (PMID 37139482, 2023). "Cox analysis showed that SMO and GLI1 gene expression levels, site of tumorigenesis, patient gender, and history of asbestos exposure were risk factors for survival time in mesothelioma patients (P < 0.05)." (PMID 37139482, 2023). "Two phase I solid-tumor trials, overall including five mesothelioma patients treated with the SMO inhibitors vismodegib (GDC-0449) or sonidegib (LDE225), reported no clinical benefit in MPM." (PMID 36358635, 2022). "Remarkably, Hh inhibition by a specific SMO inhibitor significantly suppressed cell proliferation in the mesothelioma cell lines examined." (PMID 23379358, 2013). "We also examined multiple mesothelioma cell lines for SMO expression and their cell proliferation responses to a specific SMO inhibitor." (PMID 23379358, 2013). "We also examined multiple mesothelioma cell lines for SMO expression and the effect of Hh inhibition by a specific SMO antagonist on cell proliferation by MTS assay." (PMID 23379358, 2013). "SMO and GLI1 gene expression levels, tumor site, patient's gender, and history of asbestos exposure were all risk factors for survival time in mesothelioma patients (P < 0.05), and the findings were consistent with greater significance for the prognostic value of mesothelioma." (PMID 37139482, 2023). "The expression levels of SMO and GLI1 protein and mRNA in mesothelioma tissues were higher than those in benign mesothelioma tissues." (PMID 37139482, 2023). "The Cox proportional risk model showed that gender, history of asbestos exposure, site of occurrence, SMO, and GLI1 were independent prognostic factors for mesothelioma." (PMID 37139482, 2023). "The expression levels of SMO and GLI1 protein were correlated with the age, site, and asbestos exposure history of patients with mesothelioma." (PMID 37139482, 2023). "SMO and GLI1 gene expressions in mesothelioma were negatively correlated with age, site of occurrence, and history of asbestos exposure." (PMID 37139482, 2023). "The results of Spearman's correlation analysis in 130 patients with malignant mesothelioma showed a positive correlation between SMO protein and GLI1 protein expression in mesothelioma (R = 0.673) with statistically significant differences (P = 0.000)." (PMID 37139482, 2023). "SMO and GLI1 genes were correlated with gender, age, tumor site, history of asbestos exposure, and staging of mesothelioma patients." (PMID 37139482, 2023). "SMO and GLI1 gene expression levels were negatively correlated with good prognosis in mesothelioma patients (P < 0.05)." (PMID 37139482, 2023). "SMO and protein expression of GLI1 genes had a significant effect on the survival prognosis time of patients with mesothelioma." (PMID 37139482, 2023). "RT-qPCR was applied to detect SMO and GLI1 mRNA levels in malignant mesothelioma tissues and normal mesothelial tissues, and statistical analysis showed that SMO and GLI1 mRNA expression levels were significantly higher in mesothelioma tissues than in normal mesothelial tissues (P < 0.05)." (PMID 37139482, 2023).
mesothelioma (continued). "△CtCa < △CtN indicated that the expression of SMO and GLI1 in mesothelioma tissues was higher than that in benign mesothelioma tissues; △CtCa > △CtN indicated that the expression in mesothelioma tissues was lower than that in benign mesothelioma tissues, and P < 0.05 was statistically significant." (PMID 37139482, 2023). "Further study on the expression and prognosis of SMO and GLI1 in malignant mesothelioma tissues and the relationship between the two and the molecular mechanisms of mesothelioma immunity and to further investigate the prognostic value of mesothelioma expression." (PMID 37139482, 2023). "We have also observed decreased transcriptional activities of SMO and Gli1 in mesothelioma H28 cells after Cul4A knockdown by siRNA (data not shown), suggesting that SMO is in part involved in the Cul4A-mediated Gli1 expression." (PMID 26218750, 2015). "SMO and SHH expression levels were analyzed in 46 mesothelioma tissue specimens with real-time RT-PCR, and correlation with survival was analyzed with univariate and multivariate Cox proportional hazards models, Kaplan-Meier survival curves, and the log-rank test." (PMID 23379358, 2013). "This study evaluated the factors affecting the development of malignant mesothelioma, proposed a new idea of SMO, GLI1, and immune cells as possible indicators of personalized immunotherapy and prognosis, and provided an experimental basis for finding new gene targets for mesothelioma." (PMID 37139482, 2023).
bladder cancer (6 papers, 2018 to 2024). "We speculated that PC deficiency due to STIL overexpression could inhibit the activated form of SMO and induce the activated form of GLI1 to promote tumorigenesis in bladder cancer." (PMID 37101292, 2023).
sarcoma (6 papers, 2017 to 2025). A usually aggressive malignant neoplasm of the soft tissue or bone. "Despite the controversy existing regarding the results obtained with SMO inhibitors in these types of tumours, several compounds have been (or are currently being) evaluated in sarcoma patients." (PMID 36765685, 2023). "Conversely, SMO inhibitors have not fulfilled expectations in tumours—among them sarcomas—mostly associated with ligand-dependent Hh pathway activation." (PMID 36765685, 2023). "Thus, despite evidence rendering the relationship between the Hedgehog pathway and RMS clearly manifest, SMO inhibitors are still a long way from their clinical application in this particular type of sarcoma." (PMID 36765685, 2023). "Up to date, it has been shown that miR-338 respectively targeted proto-oncogenes smoothened (SMO), Phosphatidylinositol-3,4,5-trisphosphate-dependent Rac exchange factor 2 (PREX2a), synovial sarcoma and X breakpoint 2 interacting protein (SSX2IP) respectively in several solid tumors." (PMID 28423738, 2017). "However, SMO inhibitors have not met expectations in tumours associated with ligand-dependent Hh pathway activation, such as sarcomas, colon, ovary, and pancreas." (PMID 36765685, 2023). "In sarcomas, including ES, aberrant Hh signaling is thought to be due to increased expression of GLI1, SMO, and PTCH132." (PMID 39894896, 2025).
breast tumor (5 papers, 2014 to 2021). "To test the hypothesis that breast tumours with activated GLI signalling are more susceptible to GLI inhibitors compared with upstream inhibitors targeting SMO, we chose two models, MC1 and BCM-2147." (PMID 28604738, 2017). "Thus, increased SMO-dependent GLI activation due to PTCH1 mutation or Shh induction might promote tumor recurrence by supporting the formation of chemoresistant CSC niches in breast tumors." (PMID 34572373, 2021). "Taken together, these results suggest a cooperative role of SMO-dependent (stromal compartment) and SMO-independent (epithelial compartment) GLI activation in the activation of FAK signaling in breast tumor cells to confer CSC traits and consequently to enhance chemoresistance." (PMID 34572373, 2021).
liver cancer (5 papers, 2019 to 2024). An epithelial or non-epithelial malignant neoplasm that arises from the liver. "In a highly tumorigenic CD133+ population of HCC, Smoothened (SMO) is abundantly expressed in association with the Hh signaling pathway and influences liver cancer stemness maintenance." (PMID 32466488, 2020). "In liver cancer, SMO and HDAC inhibitors showed decreased cell viability, colony formation, and increased apoptosis." (PMID 33396427, 2020). "Further, it was mentioned that in the liver cancer, SMO was a direct targeting of miR-338-3p." (PMID 31895689, 2019). "Furthermore, the expression levels of the major SHH pathway proteins Smoothened (SMO) and GLI‐1 were also significantly reduced in shRab23 liver cancer cells compared to the control." (PMID 37884351, 2024).
multiple myeloma (5 papers, 2017 to 2024). "The SMO gene encodes Smoothened protein, the chemical inhibition of which reduced stemness and proliferation of multiple myeloma CSCs." (PMID 36226253, 2022). "Studies investigating SMO as a regulator found that it was often upregulated while PTCH1 was downregulated in multiple myeloma (MM) pluripotent cells, allowing for SMO to act constitutively and maintain pluripotency." (PMID 38920995, 2024). "HH pathway activation is heterogeneous in multiple myeloma CSCs, with overexpression of the SMO gene and high Gli1 transcriptional activity." (PMID 36226253, 2022). "In multiple myeloma CSCs, it was shown that SMO and Gli1 were highly expressed in comparison to non-CSCs, and activation of HH signaling by HH ligands promoted multiple myeloma CSC's expansion, whereas inhibition of the HH signaling markedly blocked CSC's clonal expansion." (PMID 28356914, 2017).
non-small cell lung carcinoma (5 papers, 2016 to 2023). A group of at least three distinct histological types of lung cancer, including non-small cell squamous cell carcinoma, adenocarcinoma, and large cell carcinoma. "Clinical data and sequencing data from published studies and our cohort were collected to analyze the association of the mutation status of SMO with the efficacy of ICI therapy in the non-small cell lung cancer (NSCLC) cohort and the pan-cancer cohort." (PMID 36405701, 2022). "Glesatinib is a dual inhibitor of c-Met and SMO that is under phase II clinical trial for non-small cell lung cancer." (PMID 31106148, 2019). "In non-small cell lung cancer (NSCLC), blocking SMO and GLI1 induced autophagy and apoptotic responses." (PMID 26988232, 2016). "Due to the inevitable development of resistance in non-small cell lung cancer (NSCLC) with TKI treatment, the high frequency of activation of the Hh pathway and c-MET signaling initially drew attention to the dual inhibition of c-MET and SMO." (PMID 37919751, 2023).
rhabdomyosarcoma (5 papers, 2018 to 2025). A rare aggressive malignant mesenchymal neoplasm arising from skeletal muscle. "Targeting Hh pathway activation in rhabdomyosarcoma using small molecular SMO inhibitors, vismodegib, sonidegib and saridegib, has been demonstrated to inhibit growth in embryonal rhabdomyosarcoma cell lines." (PMID 40983796, 2025). "Genetic alterations, including mutations in PTCH, SUFU, and SMO lead to constitutive activation of the hedgehog pathway in BCC, rhabdomyosarcoma and MB." (PMID 31362788, 2019).
alopecia (4 papers, 2020 to 2023). Hair loss usually from the scalp. "Treatment-related non-hematologic adverse events were mostly grade 1 or 2 in severity, and the most common toxicities were consistent with SMO inhibition including dysgeusia, decreased appetite, and alopecia." (PMID 34638372, 2021). "The most frequent adverse events were like those seen with the first clinically tested SMO inhibitor vismodegib and consisted of dysgeusia, alopecia, anorexia of nausea, muscle spasms, and fatigue." (PMID 34638372, 2021). "Treatment of SMO inhibitors leads to at least a partial response in ~2/3 of advanced BCC patients, but >25% of patients discontinue therapy due to frequent, hard-to-tolerate side effects such as alopecia, dysgeusia, and muscle spasms." (PMID 36612301, 2023).
cholangiocarcinoma (4 papers, 2011 to 2021). A carcinoma that arises from the intrahepatic biliary tree (intrahepatic cholangiocarcinoma) or from the junction, or adjacent to the junction, of the right and left hepatic ducts (hilar cholangiocarcinoma). "Intriguingly, the administration of the SMO inhibitor BMS-833923 in mouse xenograft models of cholangiocarcinoma potentiates the effects of the chemotherapeutic agent gemcitabine in reducing in vivo tumor volume." (PMID 34638259, 2021). "In contrast, we found that SMO inhibition sensitized cholangiocarcinoma cells to TRAIL even after depletion of Bid, Bim, Bax, or Bak by specific siRNA, suggesting mitochondrial dysfunction is not required for TRAIL killing in this model." (PMID 21483830, 2011). "Therefore, SMO inhibitor could promote the apoptosis of cholangiocarcinoma cells as well as their metastasis." (PMID 31979397, 2020). "Both mutation and copy number alterations (CNA) affecting Hedgehog pathway main members, namely GLI1, GLI2, GLI3, SMO, PTCH1/2, SUFU, and DHH, have been observed in mixed cholangiocarcinoma patients with different frequencies." (PMID 34638259, 2021). "Suppressing the activity of SMO with cyclopamine, alone or in combination with other appropriate targeted therapies, for instance MAPKs inhibitors, resulted as being strongly effective in repressing CCA growth and survival, but also in preventing cholangiocarcinoma invasion and metastasis." (PMID 34638259, 2021).
esophageal adenocarcinoma (4 papers, 2017 to 2021). A malignant tumor with glandular differentiation arising predominantly from Barrett mucosa in the lower third of the esophagus. "SMO-independent activation of GLI1 has been detected in several malignant tumors such as esophageal adenocarcinoma whereby activated S6K1 phosphorylates GLI1 at Ser84 to induce GLI1 transcriptional activity and oncogenic functions." (PMID 33637972, 2021). "Here, we show that esophageal adenocarcinoma (EAC) cell lines are insensitive to vismodegib (SMO inhibitor) but respond to GANT61 (GLI1 inhibitor)." (PMID 32913560, 2020). "We could recently show that GLI1 is activated via ERBB2 and PI3K/AKT/mTOR in esophageal adenocarcinoma in a SMO-independent manner." (PMID 28418873, 2017). "Recent studies indicate a role of ligand- and SMO-independent non-canonical HH signaling via phosphoinositide 3-kinase (PI3K)/AKT as shown in renal cell carcinoma and esophageal adenocarcinoma or TGFβ/SMAD in pancreatic cancer." (PMID 28418873, 2017).
esophageal cancer (4 papers, 2015 to 2020). A primary or metastatic malignant neoplasm involving the esophagus. "Previous studies have reported aberrant activation of HH/GLI signaling in esophageal cancer, which can be caused by a number of factors including genetic alterations of individual pathway components, such as PTCH or SMO mutations and GLI1/2 amplification." (PMID 32913560, 2020). "Furthermore, a cross-talk between the two pathways has been described in a model of esophageal cancer where mTORC1/S6K1 promotes the oncogenic function of GLI1, through S6K1-mediated phosphorylation of GLI1, in a SMO-independent manner." (PMID 29396625, 2018). "Likewise, cotreatment with the SMO inhibitor GDC-0449 and the mTOR inhibitor RAD001 suppressed tumor growth of esophageal cancer in vivo." (PMID 25749378, 2015).
gastric tumor (4 papers, 2018 to 2023). "The initial front loading of SMO into cilia may be related to reports on gastric tumor cells which state that ARL13B directly binds and stabilizes SMO." (PMID 37830570, 2023). "In this sense efforts to select patients characterized by unusually high SMO expression in gastric tumor material with high probability to have cancers that are truly dependent on a functional Hedgehog pathway may likely yield positive results." (PMID 29725500, 2018).
lymphoma (4 papers, 2014 to 2021). A malignant (clonal) proliferation of B- lymphocytes or T- lymphocytes which involves the lymph nodes, bone marrow and/or extranodal sites. "In human lymphomas, hsa-miR-193b clearly contributes to enhancing the expression of the SMO gene and subsequently activating the GLI/Hh signaling." (PMID 27271613, 2016). "SMO stabilizes and activates TRAF6, suggesting that the SMO/TRAF6 axis can contribute to doxorubicin resistance in lymphoma." (PMID 33935743, 2021).
myeloid malignancies (4 papers, 2015 to 2025). "Glasdegib (PF-04449913; Pfizer, New York, NY, USA) is an oral SMO inhibitor, and seven clinical trials for myeloid malignancies have been reported, including four as a single agent and three in combination with other therapies." (PMID 34638372, 2021). "Herein, we report pre-clinical data of the novel combination of 5-Aza and the SMO inhibitor LDE225 in myeloid malignancies as a possible novel combination in advanced myeloid malignancies." (PMID 26483188, 2015). "Experiments with SMO inhibitors in vitro and ex vivo pharmacologically validate the idea that the HhP could serve as a therapeutic target with HMAs in myeloid malignancies." (PMID 26483188, 2015). "The efficacy of SMO inhibitors in AML suggests that they may be broadly active, but clinical studies in other myeloid malignancies have been largely inconclusive." (PMID 34638372, 2021). "This may be attributed to a compensatory effect of increased pS6, supporting the existence of SMO-independent, non-canonical regulation of Hedgehog-Gli signaling by key oncogenic drivers, as demonstrated in various myeloid malignancies." (PMID 40149597, 2025).